IL6 (interleukin 6)
Diseases named in the same sentence as IL6 in open-access papers (continued):
Sharing a sentence is not in itself a finding about the gene and the disease.
depression (continued). "Considering that previous studies noted increased IL-6 levels in patients suffering from depression, this also could be explained by the co-occurrence of depressive and psychotic symptoms in patients with SARS-CoV-2 infections." (PMID 35682084, 2022). "In addition, the effect of reducing the peripheral IL-6 level shows potential for the prevention and treatment of depression in the future." (PMID 35267944, 2022). "In a meta-analysis, it was shown that depression can be predicted by measuring IL6." (PMID 35770096, 2022). "We aimed to characterize the association between lifetime smoking and depression, as well as to assess the role that genetically-predicted C-reactive protein (CRP) level, (an archetypal generalized inflammatory marker) and/or IL-6 activity, as a potential explanation for this association." (PMID 36057695, 2022). "Correspondingly, another study found no cross-sectional associations between IL-6 and Children’s Depression Inventory (CDI), as a measure of depressive symptoms." (PMID 35292108, 2022). "The level of Interleukin 6 (IL-6), C-reactive protein (CRP) or other pro-inflammatory biomarkers can be enhanced by pro-inflammatory diets, and further raise the risk for the development of depression." (PMID 36159493, 2022). "IL-6 has also been related to mental disorders such as anxiety, depression, and suicidal behavior." (PMID 36429454, 2022). "Periodontal pathogen endotoxins are associated with elevated inflammatory parameters and proinflammatory cytokines (especially TNF α and IL‐6) that may potentiate the inflammation and increase vulnerability to depression." (PMID 34729949, 2022). "The results of the present study showed a significant difference in the mean levels of IL-6 among the three different treatment groups, which indicates that controlling stress and anxiety as well as depression is beneficial for achieving a successful treatment outcome in TMD patients." (PMID 35897358, 2022). "Depression is accompanied by the changes in the levels of inflammatory and trophic factors, including interleukins (IL-1beta, IL-2, IL-6), interferon alpha (IFN-alpha), tumor necrosis factor alpha (TNF-alpha), C-reactive protein (CRP), and brain derived neurotrophic factor (BDNF)." (PMID 35455388, 2022). "Smith (1991) revealed that cytokines like interleukin-1β (IL-1β) and interleukin-6 (IL-6) might cause hyperactivity of the HPA axis and impaired 5-HT metabolism, leading to depression." (PMID 36300881, 2022). "In addition, activated inflammatory systems, including cytokines (IL-2 and IL-6), play a crucial role in the pathogenesis of depression." (PMID 36506019, 2022). "Depression is also associated with elevated levels of inflammatory factors such as C-reactive protein (CRP), tumor necrosis factor-alpha (TNF-α), and interleukin 6 (IL-6)." (PMID 35360021, 2022). "For example, arthritis, as a chronic inflammatory disease, can increase the expression of major proinflammatory cytokines, such as tumor necrosis factor-α, interleukin-6 and interleukin-1β, which, through the brain, affect pathophysiological and neurotransmitter functions relevant to depression." (PMID 36203679, 2022). "IL-6 is another important cytokine involved in inflammation and depression." (PMID 36422176, 2022). "Besides, other studies evaluated the IL-1β, TNF-α, and IL-6, and showed that they are overexpressed in patients with depression." (PMID 35496273, 2022). "Moreover, IL-6, QUIN, TNF, and KYN showed strong individual accuracy in predicting depression risk and severity at future timepoints, with the best performance using the 2nd trimester markers to predict symptoms emerging in the 3rd trimester." (PMID 35078975, 2022). "Interestingly, BDNF emerged among the genes shared by depression and atherothrombosis, and it was well-connected to all the genes identified in both databases, namely, IL-1β, IL-6, IL-18, TNF, APOE, ACE, MTR, MTHFR genes." (PMID 35911513, 2022).
depression (continued). "Noteworthy, inflammatory processes are involved in the pathophysiology of depression and microglia dysfunction is considered a key event in depression, with patients showing increased blood concentration of proinflammatory cytokines such as IL-1β, IL-6 and TNF-α." (PMID 36232813, 2022). "For example, a study, using SEM, proposed a model that cortisol (as an indicator of Hypothalamic pituitary adrenal) predicts depression, which predicts circulating pro-inflammatory cytokines (IL-2, IL-6, TNF-α) In patients diagnosed with chronic fatigue syndrome (CFS)." (PMID 36210450, 2022). "Evidence indicated that depression and IL-6 were more closely correlated in women than in men, which may also lead to bias in our findings." (PMID 36685498, 2022). "In addition, exercise alleviated hypothalamic–pituitary–adrenal feedback regulation obstacles by modulating cortisol and IL-6 levels, and thereby improved depression." (PMID 35227300, 2022). "However, we found no statistical evidence to support that the relationship between neuronal differentiation and recurrent depression was modulated by IL6 levels in our sample." (PMID 35794184, 2022). "Moreover, among the detected inflammatory cytokines, IL-6 showed to be the most effective screening tool to predict depression, with an AUC of 0.76, a sensitivity of 79.3%, and a specificity of 67.7%, followed by TNF-α with an AUC of 0.75." (PMID 35757220, 2022). "The bivariate correlation analysis also revealed that IL-6 was positively associated with depression (r = 0.275, P = 0.019); however, the association was absent after controlling for the age effect." (PMID 35815027, 2022). "Inflammation is currently considered a potential mechanism in the development and progression of schizophrenia as well as other psychiatric disorders such as depression and bipolar disorder, with interleukin-6 (IL-6) being one of the most consistently elevated cytokines." (PMID 35873262, 2022). "Although associations between serum IL-6 and total depressive episodes were not as strong when models were corrected for BMI and maternal education (an indication of socioeconomic status)." (PMID 36277463, 2022). "Hence, serum TNF‐α, IL‐1β, IL‐6, and IL‐17 were positively related to anxiety and depression in NSCLC survivors." (PMID 34697903, 2022). "Furthermore, trials of cytokine inhibitor use in depression, such as infliximab (anti-TNFα) and sirukumab (anti-IL-6), selectively display efficacy in patients with low- inflammation levels prior to treatment." (PMID 35977923, 2022). "Indeed, there is evidence that CRP levels show less variability in individuals with depression and that IL-6, IL-8 and TNF-α levels show less variability in individuals with psychotic disorders." (PMID 36085284, 2022). "Future research into therapies blocking the pro-inflammatory cytokines IL-6 and sTNF-αR1 in hip fracture patients may provide an intervention which influences the development of depression or depressive symptoms after hip fracture." (PMID 34627160, 2021). "The significance of raised CRP and IL-6 in people with both depression and type 2 diabetes is unclear and may be important in the development of other diabetes-related complications." (PMID 33064180, 2021). "In addition, patients with unipolar depression and healthy controls also showed an AUC of 0.74, with 0.69 sensitivity and 0.70 specificity using seven variables (IL-6, carbonyl, BDNF, IL-10, IL-17A, IL-4, and TNF-α)." (PMID 33578686, 2021). "Scores of the Young Mania Rating Scale and the Hamilton Depression scale correlated with IL-6." (PMID 33683478, 2021). "In addition, compared with UCMS stress mice, LPS stress mice showed stronger expression and release of TNF-α, IL-1 β, and IL-6 in serum and depression-related brain regions (frontal cortex, hippocampus, and striatum)." (PMID 34531719, 2021).
depression (continued). "In particular, levels of IL-6 and CRP have been associated with an increased likelihood of experiencing treatment-resistant depression, suggesting that there is a role for anti-inflammatory interventions to be used as adjunctive treatments for patients with MDD." (PMID 33652997, 2021). "Observational studies and post-hoc analyses have also proposed that approximately 40% of RA patients experience major depressive disorder and/or generalized anxiety disorder and that IL-6 could potentially play a role in the pathogenesis of depression." (PMID 35056105, 2021). "The connection between IL‐6 and depression is well established." (PMID 33655551, 2021). "Furthermore, they induced TNF-α, IL-1β, and IL-6 expression NF-κB+/Iba1+ cell population in the hippocampus and corticosterone and IL-6 levels in the blood, resulting in anxiety/depression through the regulation of neuroinflammation." (PMID 33731795, 2021). "A study in cancer patients with depression showed a significant negative correlation between circulating IL-6 and BDNF, while a positive association was observed in patients with major depressive disorder." (PMID 33985854, 2021). "Elevated IL-6 levels were evaluated as predictors of future depression." (PMID 34576215, 2021). "Moreover, suicide victims with depression showed higher levels of IL-1β, IL-6 and TNF in postmortem brains, while the receptors for the production of these cytokines, such as Toll-like receptor 3 (TLR3) and TLR4, were also affected." (PMID 34827513, 2021). "Relationship between TNFα and IL-6, respectively, to fatigue, depression and pain intensity." (PMID 34248700, 2021). "IL-6 is an essential component in the cancer microenvironment orchestration and contributes to some of the adverse effects of the malignant disease (e.g., cachexia and depression)." (PMID 34681685, 2021). "This is an anti-IL6 monoclonal antibody and a phase 3 clinical candidate for rheumatoid arthritis, polymyalgia rheumatica, and temporal arteritis and also phase 2 clinical candidate for major depressive disorder." (PMID 34832866, 2021). "In a genetic rat model of depression, the decreased let-7 could increase the levels of the proinflammatory cytokine IL-6, leading to depression." (PMID 34947970, 2021). "This was evident from a study by Spalletta, which demonstrated that depression severity, especially in an acute setting, could be correlated to an increase in the levels of IL-6." (PMID 33919670, 2021). "Indeed, we previously showed that epigenetic modifications driven by gut microbiota derived metabolites, especially methylation patterns in the IL-6 promoter, promoted resilience to stress-induced depression." (PMID 34248950, 2021). "Both TNF-α and IL-6 were reported to be involved in the pathogenesis of depression." (PMID 34040528, 2021). "Conversely, clinical trials have established the therapeutic value of non-steroidal anti-inflammatory drugs (NSAID), as an adjunct to antidepressants for individuals with treatment resistant major depression by inhibiting the production of cytokines, namely IL-6." (PMID 34589733, 2021). "Small sample clinical studies have shown that XPJYD can reduce serum LPS, D-lactic acid, DAO content in patients with depression and then reduce serum IL-6 and TNF-a content, indicating that XPJYD can repair the intestinal mucosal barrier and reduce the inflammatory response to a certain extent." (PMID 34257681, 2021). "Fecal transplantation of vehicle-treated control or RS/CSS-treated mice into RS-exposed mice significantly mitigated RS-induced anxity- and depression-like behaviors, suppressed the NF-κB activation in the hippocampus and colon, and reduced the IL-6 and corticosterone levels in the blood." (PMID 34391441, 2021). "With regard to inflammatory biomarkers, sleep disorders may lead to increased levels of CPR and IL-6, and inflammatory reaction might be part of the pathophysiological process of depression." (PMID 34507561, 2021).
depression (continued). "Furthermore, running exercise reduced the protein level of IL-6 in the hippocampus of the depression model rats." (PMID 34489395, 2021). "CSS significantly reduced the RS-induced anxiety- and depression-like behaviors and hippocampal NF-κB activation and IL-6 expression, blood corticosterone level, and colonic IL-6 expression and myeloperoxidase activity, while the RS-suppressed BDNF expression increased." (PMID 34391441, 2021). "There is some evidence that certain SSRI might alleviate depression because of their effects on cytokines such as IL-6 and TNF-α." (PMID 33961667, 2021). "Depression risk is bidirectionally associated with the levels of pro-inflammatory cytokines such as tumor necrosis factor-α (TNF-α), interleukin-1β (IL-1β), and IL-6." (PMID 34475376, 2021). "Similarly, participants in the top, compared with bottom third of IL-6 at baseline had higher depression severity score at follow-up (adjusted β = 0.43; 95% C.I., 0.01–1.15; p = 0.049)." (PMID 33684738, 2021). "Concentrations of TNF and IL-6 are elevated in depressed individuals compared to healthy ones, while CRP concentrations have been associated with depression scale scores and explained 20% of the obesity-related alteration in depression scores at follow-up." (PMID 33546219, 2021). "Findings from MR analyses are consistent with a role of altered activity of the IL-6/IL-6R pathway in depressive symptoms, suggesting that this pathway could be a promising, new therapeutic target for depression." (PMID 34505025, 2021). "In addition, prolonged HPA axis hyperactivity activated by proinflammatory cytokines (IL-1, IL-6, and TNF-α) is one of the mechanisms underlying cytokine-induced depression, even in perinatal episodes." (PMID 34211407, 2021). "IL-6 was associated with negative symptoms after adjusting for depression (β = 0.09; 95% C.I., 0.01–0.22)." (PMID 33684738, 2021). "Furthermore, fecal microbiota transplantations suppressed IS-induced TNF-α, IL-1β, and IL-6 expression and NF-κB+/Iba1+ cell population in the hippocampus, resulting in the amelioration of anxiety/depression." (PMID 33731795, 2021). "Univariate logistic regression models, where depression status was the dependent variable, showed statistically significant associations with fibrinogen, IL-6, CRP and the generalised inflammation factor, but not with TNF-α." (PMID 33064180, 2021). "In people with MS and comorbid fatigue and/or depression there is reported increased serum and cerebrospinal fluid concentration of inflammatory mediators such as tumor necrosis factor, interleukins (IL-1a, IL-1b, IL-6), interferon γ and neopterin." (PMID 35242093, 2021). "Moreover, the baseline, pre-treatment levels of IL-6 positively correlated with the results of a questionnaire measuring the clinical symptoms of depression (r = 0.167, p = 0.07014)." (PMID 33920992, 2021). "The purpose of the present narrative review was to provide an integrated account of how IL-6 may contribute to development of depression." (PMID 33593388, 2021). "Our findings suggest that the IL-6 pathway could represent a putative novel target for treatment/ prevention of psychosis and depression." (PMID 33684738, 2021). "We have examined specificity and potential causality of associations for CRP and IL-6 with depressive and anxiety symptoms using large-scale data from two well-established European cohorts, UK Biobank (UKB) and Netherlands Study of Depression and Anxiety (NESDA)." (PMID 34135474, 2021). "A longitudinal study showed that high IL-6 at baseline could predict a chronic course of depression." (PMID 33653423, 2021). "Finally, a number of studies have demonstrated scaling of CRP and/or IL6 with specific phenotypic dimensions of depression (such as anhedonia, psychomotor slowing, or anxiety)." (PMID 34535766, 2021).
depression (continued). "Nevertheless, there still exists gap in our understanding of the mechanisms by which IL-6 signaling and its molecular components could possibly contribute to depression manifestation." (PMID 33593388, 2021). "Plasma levels of IL-6 and IFN-γ are associated with depression and anxiety symptoms’ severity." (PMID 34576215, 2021). "The key targets of Epicedium for treating depression were IL6, VEGFA, AKT1, and EGF." (PMID 34479552, 2021). "The increased level of proinflammatory cytokines such as IL-1β, IL-6, and IFN-γ that found in the peripheral circulation and hippocampus of depressive patients has been shown contributing to the development of depression-like behaviors in animal models with estrogen deficiency." (PMID 35155523, 2021). "Indeed, patients with major depression exhibit higher circulating IL‐6 levels than healthy controls, and IL‐6 levels decrease in response to treatment." (PMID 33655551, 2021). "-) Effects of IL-6 levels on brain morphology in depression." (PMID 33593388, 2021). "-) Possible role of IL-6 together with gut microbiota in pathogenesis of depression." (PMID 33593388, 2021). "Both TNF-α and IL-6 were reported to be involved in pathogenesis of depression." (PMID 34867356, 2021). "Additionally, STAT3 was found to associate with the SERT promoter in an IL-6-dependent manner, with the inhibition of STAT3 blocking the effect of IL-6 on 5-HT uptake in vitro and reducing depression-like behavior in vivo." (PMID 34571919, 2021). "In a report of two cases of post-COVID depression, the authors showed an association between depression and interleukins, such as IL-6, which was independent of other causes of depression that occurred during the COVID-19 pandemic (e.g., due to isolation)." (PMID 34066007, 2021). "Increased plasma IL-6 levels are among the most consistent findings in depression." (PMID 34576215, 2021). "An increase in IL-6 levels has been observed in both the acute and chronic stages of depression." (PMID 34976096, 2021). "Exposure to stressors including immobilization, antibiotics, or pathogen infection causes anxiety-like behaviors in rodents and induced the expression of proinflammatory cytokines TNF-α, IL-1β, and IL-6 in the hippocampus and colon, resulting in the occurrence of anxiety/depression and colitis." (PMID 33731795, 2021). "Psoriasis and depression can lead to the dysregulation of the gut microbiota, induce gut permeability and bacterial migration, then increases pro-inflammatory cytokines such as IL-β, IL-6, TNF-α and IFN-γ." (PMID 35004741, 2021). "The expression levels of TNF-α (p < 0.01), IL-6 (p < 0.05), and IL-1β (p < 0.01) in the CUMS group were significantly higher than those in the control group, which indicated that the occurrence of depression was associated with the production of inflammatory factors." (PMID 35185541, 2021). "Furthermore, meta-analyses assessing various cytokine levels after anti-depressant treatment in people with depression show significant decreases in IL-6, IL-1β, and CRP." (PMID 39296317, 2021). "Our results indicate that the IL-6/IL-6R pathway may represent a novel therapeutic target for schizophrenia and depression." (PMID 34280516, 2021). "Besides, patients with depression exhibit increased expression of pro-inflammatory cytokines and their receptors (e.g., IL-1, IL-6, TNF) and increased levels of chemokines in peripheral blood and cerebrospinal fluid (CSF)." (PMID 32688365, 2021). "Importantly, these differences are linked to epigenetic alterations, as blood cells from individuals with a lifetime history of depression show alterations to DNA methylation in IL-6 and CRP." (PMID 34924946, 2021). "Indeed, a clinical study on patients with suicidal depression reported elevated CSF quin-a levels in cases versus controls and a direct correlation between CSF IL-6 and CSF quin-a." (PMID 33561973, 2021).